ALB (albumin)
Diseases named in the same sentence as ALB in open-access papers (continued):
Sharing a sentence is not in itself a finding about the gene and the disease.
renal dysfunction (continued). "Univariate analysis suggested that Age≥65, Albumin ≤ 35, Renal dysfunction, Hypercalcemia, elevated LDH level, ISS III, R-ISS III, Gain 1q21, del 17p, MAF/IGH or MAFB/IGH, ASCT and VD/β-CTX at the time of MM diagnosis were risk factors for PFS in NDMM patients." (PMID 37181039, 2023). "Most interestingly, urinary adiponectin levels were already elevated at a timepoint when urinary albumin levels were still unchanged, which may point to adiponectin urine levels as an early marker for renal dysfunction." (PMID 37189804, 2023). "Therefore, this study examined the relationship between PCF formation and variables such as age, sex, radiotherapy history, surgical margin, closure type, preoperative hemoglobin, preoperative Albumin, and renal dysfunction." (PMID 37251293, 2023). "The relative risk reduction associated with sacubitril and valsartan was similar in patients with and without renal dysfunction, despite causing a modest increase in the urinary albumin to creatinine ratio." (PMID 35456336, 2022). "It is well known that serum albumin levels are decreased in individuals with liver or renal dysfunction, and these conditions may also induce the incidence of LOI." (PMID 36408675, 2022). "In the multivariate analysis of the derivation cohort, the independent predictors of in-hospital mortality and organ malperfusion identified were base excess, maximum aortic diameter ≥ 5.5 cm, renal dysfunction, D-dimer level ≥ 5.44 μg/mL and albumin amount ≤ 30 g/L." (PMID 33653281, 2021). "Although microalbuminuria is considered as the gold standard for the diagnosis of DN, renal dysfunction can also be identified through other variables including urinary albumin excretion rates, urinary albumin creatinine rates, glomerular filtration rate, HbAc1, and creatinine." (PMID 30984273, 2019). "The excretion rate of albumin into urine is considered as a routine early biomarker to assess the renal injury, such that an increase in the urinary albumin level (albuminuria) indicates the possibility of renal dysfunction." (PMID 31750312, 2019). "Serum urea, creatinine level and albumin content are used in the evaluation of renal dysfunction." (PMID 28629341, 2017). "Independent predictors of LTBI in patient with renal dysfunction were old age (odds ratio [OR]: 1.03 [1.01–1.04] per year increment), prior TB lesion on chest radiograph (OR: 2.90 [1.45–5.83]), serum albumin (OR: 2.59 [1.63–4.11] per 1 g/dl increment), and need for dialysis (OR: 2.47, [1.02–5.95])." (PMID 25919813, 2015). "Before EPVS placement, these patients had renal dysfunction and low serum albumin levels." (PMID 21777451, 2011). "In addition to respiratory dysfunction, pH, renal dysfunction (raised serum urea and creatinine) and low serum albumin were found to be independent predictors of postoperative death." (PMID 20003248, 2009). "Significant results were also shown by another blood test, as elevated liver and renal dysfunction biomarkers in a CCDS group compared to normal-aging dogs (SDMA, creatinine, total protein, urea nitrogen, albumin, AST, ALT and GGT) were found." (PMID 40872731, 2025). "Low serum albumin levels may result in specific antioxidant function or systemic protein metabolism and inflammation abnormalities, which can lead to an increase in infections, renal dysfunction, refractory ascites, and accelerate the progress of ACLF and mortality rates." (PMID 38655546, 2024). "The specific pathogenesis of renal dysfunction in patients with NKHC requires further investigation, involving measures such as urinary albumin concentration, renal imaging, and renal biopsy." (PMID 38189042, 2023). "Our data revealed that the choice to consider PEX was more likely in patients with the need for intensive care treatment, severe renal dysfunction, requirement of RRT and elevated levels of urinary albumin/creatinine ratio (uACR)." (PMID 34220805, 2021).
renal dysfunction (continued). "In the literature, urine albumin to creatinine ratio (UACR) is a precise method for measurement of albuminuria and identification of renal dysfunction." (PMID 27628850, 2016). "In patients with renal dysfunction, indeterminate QFT-GIT results accounted for 3–4%, especially in patients with malignancy or low serum albumin level." (PMID 25919813, 2015). "SHAP-based interpretation revealed that higher APACHE II scores, lower albumin levels, prolonged ICU stays, use of vasoactive agents, renal dysfunction markers (BUN, creatinine), and coagulation abnormalities (APTT) were the most influential predictors of mortality." (PMID 40761871, 2025). "Sixth, we do not have information regarding urinary albumin or protein levels, which would have allowed a more precise definition of renal dysfunction." (PMID 39135938, 2024). "Silicon nitride nanoporous-based hemodialyzers have been tested with extracorporeal circulation in rats with adenine-induced renal dysfunction and shown to clear uremic toxins without albumin spillage." (PMID 37755973, 2023). "More so, most of these studies have based their measurements on overnight albumin excretion rate (AER) as opposed to urinary albumin/creatinine ratios (ACRs), which is reliably used to measure microalbuminuria, a recognized early marker of renal dysfunction." (PMID 35910048, 2022). "Historically, albumin has been a common additive to priming solutions to maintain colloid oncotic pressure (COP) and reduce edema, while mannitol was favored to reduce postoperative renal dysfunction and act as a free radical scavenger." (PMID 36116062, 2022). "Therefore, the up-to-date AASLD guideline has recommended albumin infusion in patients with SBP and renal dysfunction." (PMID 36611386, 2022). "The recorded reduction in the levels of total protein, albumin, and globulin by TCP treatment may reflect affection of the synthetic function of the liver and/or renal dysfunction." (PMID 34564187, 2021). "Patients with increased albumin levels (N = 1083, 34.3%) were younger and less often had smaller body mass index and renal dysfunction than those with no increase in albumin levels (N = 2077, 65.7%)." (PMID 33370299, 2020). "Early involvement of paediatric nephrologists in the management of renal dysfunction, especially when there is renal dysfunction and a GFR of <90 mL/min/1.73 m2, presence of micro-albuminuria (urine albumin/creatinine 30–300 mg/g) and persistent hypertension, is recommended." (PMID 25115875, 2015). "It is noteworthy that irrespective of renal dysfunction, a lower basal serum albumin level, a higher serum AST level at post INR elevation, and comorbidity such as CHF were independent predictors of WRN." (PMID 23560034, 2013). "Serum albumin, BUN, sCr, UUN, Ucr, and Ccr are known as indicators about renal dysfunction." (PMID 21822358, 2011). "Fourth, data on other indicators such as albumin/creatinine ratio and cystatin C were not routinely collected, which may lead to inaccuracy in determining renal dysfunction." (PMID 38435350, 2024). "In the absence of a better test hypo-albuminaemia (albumin < 30g/l without hepatic or renal dysfunction) may be the best biochemical marker currently available and was used by nearly two-thirds of those surveyed." (PMID 34433498, 2021). "Additionally, some non-nutritional factors such as inflammation, fluid status, renal dysfunction, and hepatic congestion also exert diverse effects on indicators like serum albumin and BMI, effectively exposing these tools to additional noises." (PMID 35096932, 2021). "Additionally, both the serum albumin and BMI are affected by a few non-nutritional factors, including inflammation, renal dysfunction, and fluid status." (PMID 30651062, 2019). "Increased uNAG levels and reduced serum albumin may indicate the presence of unique tubular cell injuries in MCNS patients without renal dysfunction." (PMID 29179690, 2017).
renal dysfunction (continued). "Finally, we performed sensitivity analyses after excluding 125 patients with an eGFR of less than 30 ml/min/1.73 m2 to eliminate the influence of renal dysfunction on urinary albumin excretion, and the results did not change significantly (data not shown)." (PMID 24265736, 2013). "Serum biochemistry indicators of renal dysfunction (creatinine, BUN, albumin, phosphorus) were within reference ranges and were not significantly and substantially different from control group." (PMID 34867355, 2021). "However, low serum albumin level is a marker for overall sickness or pre-existing renal dysfunction, which may not be modifiable in a short time, and it is questionable whether artificial augmentation of albumin would decrease the incidence of postoperative AKI." (PMID 26302370, 2015). "Our data indicate that edoxaban reduced urinary albumin excretion in C57BL/6 mice after 5/6 nephrectomy without affecting plasma Cr levels, suggesting that this may be due to the use of mild renal dysfunction model." (PMID 35262272, 2022). "In addition to renal dysfunction, increased OPN levels at day 3 were also significantly correlated with decreased markers of liver synthesis capacity, such as albumin, pseudocholinesterase (PCHE) activity and international normalized ratio (INR)." (PMID 26111529, 2015).
Thrombocytopenia (181 papers, 2008 to 2026). A reduction in the number of circulating thrombocytes. "These three variables were then incorporated into a new diagnostic model, termed the AST-thrombocytopenia-albumin (ATA) Score." (PMID 40361937, 2025). "The importance of each potential risk factor obtained by ANN model analysis showed that urea, baseline platelet value, and ALB were among the top three possible risk factors for linezolid-induced thrombocytopenia predicted by the ANN model." (PMID 38449807, 2024). "These factors include total dose of oxaliplatin, baseline platelet count, M stage, albumin, and natural killer cells, which have demonstrated a good predictive effect on risk for thrombocytopenia in patients with CRC treated with oxaliplatin." (PMID 39371844, 2024). "Lower counts of total and segmented leukocytes, higher counts of banded leukocytes, thrombocytopenia, and lower serum albumin levels are significantly associated with mortality." (PMID 36551439, 2022). "We have not observed association between its application and significant thrombocytopenia or more significant decrease in albumin concentration." (PMID 32292492, 2020). "Fig 4demonstrates Kaplan-Meier survival estimates according to key clinical trial exclusions, demonstrating that thrombocytopenia, increased creatinine, low albumin, and high bilirubin were associated with decreased survival at 2 years." (PMID 33270648, 2020). "Our study has also linked decreased albumin concentration and greater severity of thrombocytopenia (i.e., lower platelet count)." (PMID 25674854, 2015). "However, both studies demonstrated that cardiac and renal comorbidities, HE, thrombocytopenia, TB >3.5 mg/dL, and serum albumin <2.65 mg/dL were associated with worse outcomes." (PMID 40900573, 2025). "In addition to thrombocytopenia, our study firstly found that the levels of serum albumin and hemoglobin was independently associated with the risk of infection." (PMID 34418967, 2021). "Furthermore, multiple linear regression analysis revealed that advanced age, higher triglyceride levels, lower albumin levels, and lower cholesterol levels were independently associated with thrombocytopenia." (PMID 25674854, 2015). "However, thrombocytopenia and low serum albumin, which have been identified as the key risk factors for hepatic decompensation and death under triple therapy before, were also associated with occurence of a SAE in the univariate analysis in our cohort." (PMID 24884400, 2014). "Our univariate and multivariate logistic regression analyses revealed that lower ALB and higher ALT, ALP, and TBIL were independent factors significantly associated with an increased risk of thrombocytopenia." (PMID 40510350, 2025). "Our multivariate logistic regression analyses revealed that higher TBIL, lower ALB, higher ALT, and higher ALP were independent factors significantly associated with the risk of thrombocytopenia in HBV infection subjects." (PMID 40510350, 2025). "Common poor prognostic factors include advanced age, high ferritin levels, thrombocytopenia, prolonged prothrombin time, low serum albumin, and elevated lactate dehydrogenase levels." (PMID 39997452, 2025). "Individuals with thrombocytopenia had lower levels of ALB but higher levels of Age, FIB-4, TBIL, DBIL, ALT, AST and ALP." (PMID 40510350, 2025). "This showed that the incidence of thrombocytopenia in the albumin-bound paclitaxel group was 61% of that in the paclitaxel group." (PMID 40900779, 2025). "In previous studies on prognostic factors in HFRS that included more than 100 patients, several laboratory variables—C-reactive protein, total bilirubin, albumin, thrombocytopenia, and proteinuria—were reported as significant prognostic markers." (PMID 40072771, 2025).
Thrombocytopenia (continued). "Among laboratory abnormalities, thrombocytopenia (42.5%) and decreased albumin (40.0%) were most frequently observed, with AST elevation (32.5%), neutropenia (25.0%), ALT elevation (20.0%), and elevated total bilirubin (20.0%) also commonly reported." (PMID 40821815, 2025). "The most common adverse reactions were elevated transaminases, thrombocytopenia, decreased albumin, abdominal pain, nausea, and vomiting." (PMID 39660127, 2024). "Other laboratory markers obtained in the acute phase of MIS-C have been associated with PICU admission, like elevated ESR (>30 mm/h), CRP (>5 mg/dL), ferritin, PCT, thrombocytopenia, lymphopenia, hyponatremia, and decreased serum albumin levels." (PMID 39338265, 2024). "Specifically, albumin levels correlated with proteinuria (r = 0.49, p < 0.001), thrombocytopenia (r = −0.54, p < 0.001), mean UtA-PI (r = 0.42, p = 0.003), onset of PE (r = −0.41, p = 0.003), and newborn mass (r = −0.37, p = 0.009)." (PMID 39408980, 2024). "Cluster H1 also had higher levels of thrombocytopenia and lower serum albumin levels when compared to the other clusters." (PMID 39108993, 2024). "Significantly higher HB antigen and INR values and significantly lower platelet counts (moderate thrombocytopenia) and albumin levels were observed in cirrhotic patients compared to non-cirrhotic ones." (PMID 39338984, 2024). "The decrease in albumin can reduce the protein binding rate of Linezolid in plasma and alter its distribution, leading to increased drug exposure and the occurrence of thrombocytopenia." (PMID 38449807, 2024). "Although the lymphoma group presented with thrombocytopenia, decreased albumin, elevated lactate dehydrogenase and carcinoembryonic antigen, hepatomegaly, and splenomegaly, these features did not make a diagnosis separately." (PMID 36884116, 2023). "Laboratory parameters like thrombocytopenia of less than 1.5 lakhs/cu.mm (52.8%), albumin <3 g/dL (60.4%), and reversal of albumin/globulin ratio (52.4%) were significant predictors of esophageal varices." (PMID 37565128, 2023). "In the lymphoma group, thrombocytopenia, decreased albumin, and elevated LDH and carcinoembryonic antigen were observed." (PMID 36884116, 2023). "After adjusting for age, sex, hemoglobin, albumin, ALT/TB, and pleural effusion, thrombocytopenia remained independently associated with shock, ICU admission, and mortality in patients with PLA." (PMID 37560317, 2023). "Albumin < 30 g/L, thrombocytopenia and aspartate aminotransferase (AST) > 40 U/L were associated with HBsAg positivity." (PMID 36431096, 2022). "We found that poor prognostic factors such as advanced age, male gender, neutropenia, lymphopenia, low albumin, thrombocytopenia, and GFR and high AST, creatinine, LDH, CK, ferritin, CRP, procalcitonin, and D-dimer were common in these two groups." (PMID 35685537, 2022). "The multivariate logistic regression analysis showed that thrombocytopenia (p = 0.001), ALB < 30g/L (p = 0.024), and AST > 40 U/L (p = 0.004) were characteristic of the HBsAg-positive cases." (PMID 36431096, 2022). "Several models for G ≥ 3 thrombocytopenia exploring a number of covariates (i.e., dose, platelets at baseline, albumin, AAG, BSA) were examined." (PMID 34739582, 2022). "An Emax logistic model for G4 neutropenia and a linear logistic model for G ≥ 3 thrombocytopenia, which retained platelets and albumin at baseline and body surface area, best fitted to AUCtot and AUCu." (PMID 34739582, 2022). "The levels of albumin (ALB) and total protein (TP) were reduced below normal range in the thrombocytopenia patients at 11–20 days or 21–30 days after symptom onset." (PMID 35791362, 2022). "According to our study results, patients with high-risk FIB-4 scores were predominantly male, of advanced age, with neutropenia, lymphopenia, low albumin, thrombocytopenia, and GFR, and high AST, creatinine, LDH, CK, ferritin, CRP, procalcitonin, and D-dimer." (PMID 35685537, 2022).